VDR (vitamin D receptor)
Diseases named in the same sentence as VDR in open-access papers (continued):
Sharing a sentence is not in itself a finding about the gene and the disease.
vitamin D deficiency (continued). "Vitamin D/VDR plays a very important role in vestibular function, and VDR-deficient mice show a decreased equilibrium function, suggesting that vitamin D deficiency may lead to vestibular dysfunction." (PMID 37064183, 2023). "These polymorphic forms of VDR may be associated with decreased VDR activity, reduced vitamin D actions, vitamin D deficiency and increased risk for development of vitiligo." (PMID 35318513, 2023). "Still, it has been proposed that inherited gene polymorphisms in the genes related to the vitamin D-binding protein (DBP), vitamin D receptor (VDR), and vitamin D 1alpha-hydroxylase (CYP1alpha) are connected to the potential role of vitamin D deficiency in insulin resistance." (PMID 37764823, 2023). "Vitamin D deficiency and the VDR Fok I polymorphism may constitute independent risk factors for susceptibility to COVID-19 in Egyptian children and adolescents." (PMID 36085364, 2023). "Vitamin D deficiency and VDR Fok I polymorphism may constitute independent risk factors for susceptibility to COVID-19 in Egyptian children and adolescents." (PMID 36085364, 2023). "The mutated A allele of VDR gene BsmI polymorphism present in people with hypolactasia may contribute to an increased risk of vitamin D deficiency." (PMID 37373338, 2023). "The AA variant of the VDR gene’s BsmI polymorphism present in people with hypolactasia may further contribute to an increased risk of vitamin D deficiency." (PMID 37373338, 2023). "There is evidence that vitamin D deficiency and VDR expression in adipocytes are linked to obesity." (PMID 37063318, 2023). "Of note, our logistic regression model revealed that vitamin D deficiency and the VDR Fok I FF genotype were independent risk factors for COVID-19 among the studied patients controlling for age, sex, season at enrollment, and household crowding as potential confounders." (PMID 36085364, 2023). "Additionally, the VDR gene is very important in Saudi Arabia, as almost 60% of the population exhibits a vitamin D deficiency." (PMID 37836571, 2023). "This suppressive effect could imitate vitamin D deficiency [25(OH)D < 20 ng/mL]52 conditions associated with low VDR protein expression levels in skeletal muscle." (PMID 37612333, 2023). "Additionally, vitamin D receptor (VDR) expression in the adipose tissue seems to be associated with vitamin D deficiency in obesity." (PMID 37242192, 2023). "The current study supported that in presence of vitamin D deficiency, C-variant of FokI polymorphism in VDR gene may represent a genetic risk factor for progression to local pneumonia complications." (PMID 37559014, 2023). "However, another study also showed that swimming improved serum 25(OH)D levels and the expression of VDR in some tissues of diabetic rats with vitamin D deficiency, thereby exerting the beneficial effects of exercise." (PMID 36771445, 2023). "Regarding the possible mechanisms by which vitamin D is related to muscle function, there is evidence in experimental studies indicating that vitamin D deficiency is associated with lower VDR content, increased oxidative stress, and altered activity of antioxidant enzymes in skeletal muscle." (PMID 35565827, 2022). "A direct role for the VDR in regulating skeletal muscle mitochondrial respiration in vitro has been reported, providing a potential mechanism as to how vitamin D deficiency might impact upon skeletal muscle oxidative capacity." (PMID 36434267, 2022). "A recent study found that PFOA may act as an antagonist on the Vitamin D receptor, possibly contributing to a functional vitamin D deficiency." (PMID 36402982, 2022). "In the case of vitamin D deficiency, VDR filling is insufficient, which may interfere with the normal function of hormonal processes to prevent brain diseases, leading to emotional disorders and depression." (PMID 36245527, 2022).
vitamin D deficiency (continued). "Since vitamin D deficiency is endemic in the Saudi population, this group is susceptible to the adverse effects of vitamin D-related disorders, given the presence of the relatively ineffective longer VDR protein found in women with the ff VDR genotype." (PMID 35282461, 2022). "Some investigators reported that the prevalence of vitamin D deficiency or insufficiency was high in juvenile idiopathic arthritis; however, it was unassociated with either intensity of inflammation or the genotypes of the vitamin D receptor." (PMID 35458206, 2022). "Previous studies suggested that vitamin D deficiency or defective VDR may be detrimental to cardiovascular health and other diseases, such as cancer, infectious and autoimmune diseases." (PMID 35783863, 2022). "Lung NFs from BALB/c mice administered with calcitriol showed higher expression of VDR than that of appropriate controls (1000 IU and 100 IU), whereas lung NFs from mice in both vitamin D deficiency and supplementation groups showed lower VDR expression than that of control (1000 IU) mice." (PMID 36230508, 2022). "For patients with vitamin D deficiency, recent studies have suggested that a genetic relationship between patients with VDR and CYP2R1 gene variants may be linked to the deficiency." (PMID 35629892, 2022). "It is well-documented that the presence of VDR on the surface of macrophages, lymphocytes and gut epithelial cells represents the key factor linking vitamin D deficiency, VDR dysfunction and altered gut microbial composition, eventually leading to the onset of several chronic conditions." (PMID 36292016, 2022). "In addition, vitamin D deficiency can increase inflammation, enhance inflammatory cytokines expression, and inhibit VDR expression and activity." (PMID 35967812, 2022). "Calcidiol 1-monooxygenase enzyme, also known as the VDR gene, regulates the active form of Vitamin D. Vitamin D is an active regulator of the immune response and Vitamin D deficiency has been associated with a more aggressive form of COVID-19 and poor prognosis." (PMID 36672763, 2022). "VDR and the 1-hydroxylase enzyme are present in pancreatic β-cells, and 1,25(OH)2D has been shown to act on pancreatic cells overwhelmed by inflammation and vitamin D deficiency." (PMID 36043008, 2022). "The aim of this study was to evaluate the prevalence of vitamin D deficiency, its correlation to RA disease activity, and correlation to disability scores, as well as to determine a possible association between VDR gene polymorphisms and RA susceptibility in the Lithuanian population." (PMID 33916688, 2021). "The molecular evidence for the link between vitamin D deficiency and preeclampsia has primarily been established from studies that used constitutive mouse knock-outs of either the VDR or the enzyme 1 alpha-hydroxylase, which is responsible for the production of the active vitamin D hormone." (PMID 34959804, 2021). "Aside from VDR gene polymorphisms, prenatal vitamin D deficiency may also influences the risk of kidney stone formation." (PMID 33956883, 2021). "Inactivating VDR mutations or vitamin D deficiency during development results in rickets, hypocalcemia, secondary hyperparathyroidism, and hypophosphatemia, pointing to the critical role of 1,25(OH)2D3‐induced signaling in the maintenance of mineral homeostasis and skeletal health." (PMID 34950832, 2021). "The evidence suggests that VDR polymorphisms and vitamin D deficiency can increase the risk of osteoporosis, calcium stones, diabetes, and prostate cancer 17 and the first may affect development and growth processes." (PMID 34936251, 2021). "The increased release of cytokines in the presence of vitamin D deficiency may be associated with the VDR, a transcription factor that mediates the genomic effects of calcitriol, which is constitutively expressed in monocytes and macrophages." (PMID 34576172, 2021). "GC: gastric cancer; VD: vitamin D; VDD: vitamin D deficiency; VDR: vitamin D receptor." (PMID 34722053, 2021).
vitamin D deficiency (continued). "Vitamin D deficiency or VDR gene polymorphism increases the risk of cirrhosis." (PMID 34615940, 2021). "VDR mediates the genomic actions of vitamin D. It has been proposed that VDR may act as a druggable target for NAFLD in light of the discovery of vitamin D deficiency in NAFLD patients." (PMID 34745420, 2021). "The presence of enzymes CYP2R1 and CYP27B1 and the detection of vitamin D receptor expression in testicular tissue as well as evidence for clinically relevant vitamin D deficiency in hypogonadal men suggested a prominent role of the testis in the metabolism of this vitamin." (PMID 34107893, 2021). "Moreover, an association between vitamin D deficiency with VDR gene polymorphisms has been reported in PCOS." (PMID 34684492, 2021). "Moreover, the impact of vitamin D deficiency increases the reduction in age expression of skeletal muscle vitamin D receptor." (PMID 33920130, 2021). "Moreover, vitamin D deficiency decreased gut vitamin D receptor (VDR) expression and this, in turn, generated dysbiosis." (PMID 33924419, 2021). "Consequently, patients with pseudo-vitamin D deficiency, VDR knockout mice, and 1-α-hydroxylase knockout mice show defective decidualization, inadequate uterine development, and anovulation, respectively." (PMID 34155552, 2021). "This study investigated several determinants for serum vitamin D levels, as well as whether the VDR gene's TaqI polymorphism is associated with vitamin D deficiency and insufficiency." (PMID 33029399, 2020). "Moreover, the insulin gene is transcriptionally regulated by VDR in pancreatic β cells, and vitamin D deficiency reduces insulin secretory response to carbohydrate loading in experimental models." (PMID 33126575, 2020). "Different variants in the loci of genes (such as DHCR7, CYP2R1, CYP24A1, and GC) that are responsible for vitamin D synthesis, hydroxylation, and transport, as well as VDR gene polymorphisms, may be associated with the risk of vitamin D deficiency." (PMID 33330279, 2020). "Also, the results obtained by Jedrzejul and colleagues were suggestive of a lack of association among the homogeneous classic PCOS phenotype, vitamin D deficiency, and VDR gene polymorphisms in lower Silesian women." (PMID 33134800, 2020). "We presume that the collateral pathway represented by the large vessels of the Willis circle is impaired in VDR inactivity since we reported previously that vitamin D deficiency induces morphological alterations and impaired endothelium-mediated vasodilation in anterior cerebral arteries." (PMID 32545499, 2020). "Vitamin D deficiency could raise hepatic cholesterol biosynthesis that is involved in the reduction of transcriptional activity of VDR, downregulation of insulin-induced gene-2 (INSIG2) expression and alteration of INSIG-2/SREBP-2 pathway." (PMID 32326217, 2020). "Evidence from population studies suggests that vitamin D deficiency is highly prevalent among the general population in China, which may be related to genetic variation in VDR." (PMID 32000758, 2020). "Different variants in the loci of the genes responsible for the synthesis, hydroxylation, and transport of vitamin D (such as DHCR7, CYP2R1, CYP24A1, and GC), as well as VDR gene polymorphisms may also be associated with the risk of vitamin D deficiency." (PMID 33330279, 2020). "Recent findings suggest that vitamin D deficiency may be a risk factor for those carrying certain genotypes of the VDR gene." (PMID 31912198, 2020). "Besides the link between vitamin D effectivity (vitamin D deficiency or VDR polymorphism) and cognitive decline the mechanism underlying is poorly understood." (PMID 32554862, 2020). "The variant in VDR rs59128934 (allele G) was associated with risk to vitamin D insufficiency (OR 2.07; 95% CI 1.28–3.34; p = 0.002) as well as to deficiency (OR 1.78; 95% CI 1.12–2.83; p = 0.014), when compared to controls, ≥ 30 ng/mL and ≥ 20 ng/mL, respectively." (PMID 32834827, 2020).
vitamin D deficiency (continued). "One study reported that VDR single nucleotide polymorphisms and haplotypes may determine how inflammatory markers change in breast cancer survivors with vitamin D deficiency, following vitamin D supplementation." (PMID 31252594, 2019). "Based on the current knowledge we propose that vitamin D deficiency results from the loss of VDR function and it could be partly responsible for the development of neurodegenerative diseases in human beings." (PMID 30830277, 2019). "A recent study pointed that down-regulation of VDR expression and vitamin D deficiency may contribute to phenotypic changes of inflammatory patterns in maternal vasculature in preeclampsia." (PMID 31892349, 2019). "Vitamin D deficiency and vitamin D receptor (VDR)/vitamin D binding protein (VDBP) gene variants could play an important role in susceptibility to PCOS and contribute to metabolic disturbances and menstrual dysfunction." (PMID 31870342, 2019). "Thus, the aim of the current study was to examine the prevalence and severity of vitamin D deficiency and the association of VDR polymorphism with risk of breast cancer in Ethiopia." (PMID 30699973, 2019). "Moreover, vitamin D deficiency showed a different clinical outcome depending on the VDR-rs2227850 status, being an independent predictor of a detrimental lipid profile in AG/AA-patients, but not in their GG-counterparts." (PMID 30796319, 2019). "High levels of retinol combined with vitamin D deficiency could hinder binding of VDR to the heterodimer RAR-RXR and thus block the effects of vitamin D." (PMID 31557195, 2019). "Probably, in obese subjects, the insufficient sun exposure and outdoor activities and the altered expression of the vitamin D receptor (VDR) among adipose tissue could represent the principal factors of the association between obesity and vitamin D deficiency." (PMID 31266190, 2019). "We assume that vitamin D deficiency results from the loss of VDR function and it could be partly responsible for the development of neurodegenerative diseases in human beings." (PMID 30830277, 2019). "Our findings suggest that vitamin D deficiency and VDR gene polymorphisms may contribute to the development of some MS components in adult female population." (PMID 30166978, 2018). "Active vitamin D metabolites can downregulate inflammatory markers via the nuclear VDR expressed in antigen-presenting cells, and vitamin D deficiency may result in increased pro-inflammatory cytokines that impact muscle strength and performance." (PMID 30180822, 2018). "Due to the anti-inflammatory and barrier-strengthening properties of VDR signaling, cirrhosis-associated systemic inflammation and dysfunction of intestinal barriers might be promoted by vitamin D deficiency." (PMID 30408125, 2018). "Thus, vitamin D deficiency predictably caused a decrease in VDR expression and this alteration influenced the TGF-β1 expression in VDD+Nx rats." (PMID 30370270, 2018). "Thus, this cross-sectional study was aimed to examine the association between BsmI (rs1544410) VDR gene polymorphism with vitamin D deficiency, adiposity and insulin resistance in our adolescents." (PMID 28617856, 2017). "The possible causes for the high prevalence of vitamin D deficiency among Iranian women are sun light avoidance, skin pigmentation, insufficient intake of vitamin D in the Iranian diet and specific polymorphism in vitamin D receptor and vitamin D-binding protein." (PMID 29202122, 2017). "Furthermore, in vitamin D deficiency is endothelial function of placental vessels disturbed and VDR expression on placental endothelium disturbed." (PMID 29113124, 2017). "The different response to vitamin D supplementation could be explained by VDR gene polymorphism involved in vitamin D receptor, which results in vitamin D deficiency at 36 PMA in some babies after supplementation." (PMID 28472980, 2017).
vitamin D deficiency (continued). "Possible contribution of other VDR genes as well as interaction with environmental factors such as dietary supplements and physical activities needs to be further investigated to fully understand the role of this SNP in vitamin D deficiency in our population." (PMID 28617856, 2017). "GDM is an pro-infammatory state and VDR upregulation seems to compensate Vitamin D deficiency." (PMID 29113124, 2017). "Vitamin D deficiency, certain vitamin D receptor (VDR) gene polymorphisms, and alterations of vitamin D binding proteins (VDB) and of their genes may be involved in the onset of AT." (PMID 27571093, 2016). "As vitamin D deficiency results in downregulation of VDR expression, impairment of muscle contraction may be expected after vitamin D deficiency." (PMID 26906744, 2016). "In the current study, we indeed observed a downregulation of the VDR with vitamin D deficiency in both muscles, which could eventually explain the loss of muscle force with vitamin D deficiency." (PMID 26906744, 2016). "However, we were unable to show a direct effect of vitamin D deficiency on surfactant measures or VDR expression." (PMID 27571350, 2016). "Interestingly, vitamin D deficiency was also associated with downregulation of the expression of vitamin D receptor (VDR), FOXP3 (a transcription factor associated with Treg cells), and retinoic acid receptor (RAR)." (PMID 27089367, 2016). "This study investigated whether vitamin D receptor gene polymorphisms are altered in primary open-angle glaucoma subjects carrying the risk allele, and whether vitamin D deficiency is an important factor in the development of glaucoma." (PMID 27435453, 2016). "Similarly, another study associated vitamin D deficiency and VDR activity with changes in leukocyte DNA methylation." (PMID 28066436, 2016). "However, only a few studies have reported an association between vitamin D deficiency or vitamin D receptor gene polymorphism and NTM disease." (PMID 26812154, 2016). "In this study, we will evaluate whether vitamin D deficiency and Cdx-2, FokI, BsmI and TaqI polymorphisms of the VDR gene are associated with POAG in the Han population of China." (PMID 27435453, 2016). "Similarly, a previous animal study showed that vitamin D deficiency or VDR knockout impaired the ability of insulin secretion and induced hyperglycemia." (PMID 25774877, 2015). "Vitamin D deficiency is recognized as a worldwide epidemic, especially in the elderly, as a result of decreased sun exposure and, consequently, decreased intrinsic synthesis, lower dietary intake, and decreased vitamin D receptor (VDR) activity." (PMID 26091351, 2015). "The VDR gene is the most widely studied genetic factor implicated in vitamin D deficiency." (PMID 26540116, 2015). "Notably, epidemiological studies show that vitamin D deficiency, as well as specific polymorphisms in the VDR gene, are strong prognostic factors for development and severity of CRC." (PMID 26260259, 2015). "The role of VDR and susceptibility to TB is also under debate but the active metabolite of vitamin D (1,25-dihydroxyvitamin D3) suppresses the growth of M. tuberculosis in vitro and vitamin D deficiency has been associated with susceptibility to active TB." (PMID 26643661, 2015). "In addition, similarly to another study, vitamin D deficiency has been found to contribute to the increased rate of falls, indicating a significant relationship between falls and VDR gene polymorphisms." (PMID 26699707, 2015). "We were therefore interested to determine whether the strength of association between profound vitamin D deficiency and delayed sputum smear conversion differed according to genetic variation in VDR, DBP and CYP2R1." (PMID 26193879, 2015). "It is also plausible that vitamin D deficiency may lead to diminished vitamin D receptor (VDR) in type II muscle fiber (see recent review), and thus have a direct influence on muscular weakness, or conversely, strength improvement, with supplementation." (PMID 24883075, 2014).